RUNX1 (RUNX family transcription factor 1)
Diseases named in the same sentence as RUNX1 in open-access papers (continued):
Sharing a sentence is not in itself a finding about the gene and the disease.
prostate carcinoma (31 papers, 2009 to 2024). A carcinoma that arises from epithelial cells of the prostate gland. "On the other hand, better clinical outcomes are associated with patients with higher levels of RUNX1 expression in both breast and prostate cancer patients." (PMID 38361095, 2024). "Although mainly known as a master regulator of hematopoiesis, RUNX1 is increasingly implicated in hormone-associated epithelia including malignant conditions such as prostate cancer." (PMID 33025905, 2020). "Our study, for the first time, identifies changes in Runx1 and Runx2 that are associated with molecular markers of human prostate cancer progression." (PMID 27634876, 2016). "Low RUNX1 expression in prostate cancer tissues was associated with poor cancer-specific survival of the patients." (PMID 25537508, 2015). "Therefore, in addition to the role of the androgen-RUNX1 association in prostate cancer, such pathway is also involved in GC progression among males." (PMID 35096085, 2022). "The RUNX1 expression in prostate cancer tissues was negatively associated with poor prognosis." (PMID 32498288, 2020). "RUNX1 has been shown to be androgen-dependent, and loss of RUNX1 may contribute to prostate cancer progression." (PMID 31592165, 2019). "Using the TRAMP mouse model of human prostate cancer, we address mechanisms of deregulation for the cancer-associated transcription factors, Runx1 and Runx2 by identifying microRNAs with reciprocal expression changes at six time points during 33 weeks of tumorigenesis." (PMID 27634876, 2016). "Our findings also highlighted the significance of RUNX1 loss in the progression of prostate cancer." (PMID 25537508, 2015). "Importantly, low expression of RUNX1 is associated with poor prognosis of the patients and high Gleason score in our clinical prostate cancer samples." (PMID 25537508, 2015). "Next, we analyzed the role of RUNX1 in prostate cancer cells and its association with AR." (PMID 25537508, 2015). "RUNX1 expression has been shown to be regulated by AR in human prostate cancer and triple negative breast cancer cells in vitro and ReMap ChIP-seq data reveals AR binding sites on mouse Runx1 and -2 promoter and intronic areas." (PMID 38630262, 2024). "Abnormally elevated RUNX1 levels in prostate cancer promote the EMT phenotype and activate the Akt/P38/JNK-MAPK signaling pathway driving the invasion and metastasis of prostate cancer cells." (PMID 38430423, 2024). "Overall, our approach first demonstrated that RUNX1 enhanced EMT-driven prostate cancer metastasis and that HA was capable of inhibiting the EMT and metastatic processes and should probably be considered as a candidate for metastasis PCa treatment." (PMID 37367670, 2023). "RUNX1 expression can predict a better outcome for patients with prostate cancer, but plays a dual role in promoting or inhibiting the progression of this cancer." (PMID 35534796, 2022). "miR-141 induces prostate cancer cell apoptosis via targeting Runt-related transcription factor 1 (RUNX1)." (PMID 36158660, 2022). "RUNX1 knockdown decreased the expression of TMPRSS2 in the human prostate cancer cell line, whereas increased the expression of CTSB/L genes." (PMID 34407143, 2021). "For example, RUNX1 promoter is regulated by EZH2 (enhancer of zeste homolog 2)-dependent histone H3 lysine 27 (K27) trimethylation in prostate cancer cells." (PMID 32498288, 2020). "For example, in ovarian and skin cancers, RUNX1 has been identified as an oncogene, while it exerted tumor suppressive effect in lung and prostate cancers 35-38." (PMID 32549768, 2020). "For example, the ectopic expression of RUNX1 in esophageal adenocarcinoma cells reduced the anchorage-independent growth, and the knockdown of RUNX1 by siRNAs enhanced androgen-independent proliferation of prostate cancer cells." (PMID 32498288, 2020).
prostate carcinoma (continued). "The RUNX1 expression level in clinical prostate cancer tissues is negatively associated with EZH2 expression, and decreased RUNX1 expression is correlated with poor prognosis." (PMID 28264478, 2017). "Using the TRAMP-C2 cell line, which provides an in vitro model to elucidate molecular mechanisms of prostate cancer, we assessed the functional activities of Runx1 and Runx2 in PCa." (PMID 27634876, 2016). "In clinical prostate cancer samples, the RUNX1 expression level is negatively associated with EZH2 and that RUNX1 loss correlated with poor prognosis." (PMID 25537508, 2015). "To analyze global transcriptional function, we then extensively mapped RUNX1 binding sites in the prostate cancer genome and identified RUNX1 is recruited to AR binding sites by direct interaction with AR." (PMID 25537508, 2015). "Further characterization of RUNX1-transcriptional networks and clinical analyses in context-specific conditions would reveal further details of prostate cancer progression." (PMID 25537508, 2015). "In both prostate cancer and benign regions, RUNX1 is highly expressed in the nucleus, however, the labeling index (LI) of RUNX1 is decreased in prostate cancer tissues with a high Gleason score." (PMID 25537508, 2015). "Taken together, our results showed that RUNX1 plays a critical role in androgen-dependent and –independent prostate cancer cell growth." (PMID 25537508, 2015). "Cell proliferation assays indicate the positive role of RUNX1 in androgen-dependent prostate cancer growth." (PMID 25537508, 2015). "By investigating the histone modification of genes in prostate cancer, we found that the RUNX1 promoter is occupied with H3K27me3 and that EZH2 is bound to the region." (PMID 25537508, 2015). "We also observed that repression of RUNX1 by EZH2 enhanced androgen-independent prostate cancer cell growth." (PMID 25537508, 2015). "RUNX1 expression is necessary for AR signaling and androgen-dependent prostate cancer cell proliferation." (PMID 25537508, 2015). "In summary, this is the first report that both AR and EZH2 regulate RUNX1 and that RUNX1 was shown to have differential functions in androgen-dependent and androgen-independent prostate cancer cells." (PMID 25537508, 2015). "In the present study, we first analyzed RUNX1 function in androgen-dependent prostate cancer growth because we found that RUNX1 expression is induced by androgen treatment." (PMID 25537508, 2015). "In the present study, we demonstrated the molecular mechanism and clinical significance of RUNX1 expression in prostate cancer." (PMID 25537508, 2015). "The downstream signals of RUNX1 in AR-negative prostate cancer cells require investigation to understand the specific role of RUNX1 in growth inhibition in AR-independent prostate cancer." (PMID 25537508, 2015). "In AR-negative cell lines, RUNX1 knockdown enhances, while RUNX1 overexpression inhibits, the growth of prostate cancer cells." (PMID 25537508, 2015). "Enhancer of zeste homolog 2 (EZH2), which is a major contributor to androgen-independent signaling in prostate cancer, represses RUNX1 transcription, and the expression of RUNX1 is negatively associated with EZH2 in clinical samples." (PMID 25537508, 2015). "Moreover, runt-related transcription factor 1 (RUNX1) acts as an oncogene in prostate cancer, but little is known about its role in the EMT." (PMID 37367670, 2023). "This in turn could lead to the development of an effective prognostic RUNX1 factor and targeted therapy for advanced-stage prostate cancer, which requires further exploring in mammalian models." (PMID 37367670, 2023). "Interestingly, RUNX1 promotes the development of ovarian and skin cancers, but exhibits tumor-suppressive activity in lung and prostate cancers." (PMID 35534796, 2022).
prostate carcinoma (continued). "Although the prostate gland phenotypes have not been reported, a study in which ChIP-seq analysis was performed recently demonstrated that RUNX1 is recruited to androgen receptor binding sites and that Runx1 positively regulates androgen-dependent prostate cancer growth." (PMID 28877240, 2017). "Thus, miRNAs that target Runx1 or Runx2 and are deregulated during prostate tumorigenesis present exciting candidates for novel therapeutic intervention in men diagnosed with prostate cancer." (PMID 27634876, 2016). "Runx1 is uniquely targeted by miR-139-5p and miR-382-5p, neither miRNA has been extensively examined in association with prostate cancer." (PMID 27634876, 2016). "Furthermore, qRT-PCR and luciferase analysis also showed that RUNX1 knockdown resulted in the inhibition of androgen-mediated gene and AR transcriptional activity in prostate cancer cells." (PMID 25537508, 2015). "Next, we analyzed the role of RUNX1 in AR-negative prostate cancer cells." (PMID 25537508, 2015). "We also confirmed RUNX1 induction by androgen in other AR positive prostate cancer cells." (PMID 25537508, 2015). "In addition, our clinical study indicated that low expression levels of RUNX1 would be an indicator of poor prognosis of prostate cancer patients." (PMID 25537508, 2015). "We explored the role of RUNX1 in prostate cancer cell proliferation." (PMID 25537508, 2015). "Here, we report that runt-related transcription factor (RUNX1) could be a key molecule for the androgen-dependence of prostate cancer." (PMID 25537508, 2015). "Furthermore, we showed that RUNX1 expression is correlated with a good prognosis for prostate cancer patients." (PMID 25537508, 2015). "We unexpectedly identified a dual role for RUNX1 in prostate cancer progression." (PMID 25537508, 2015). "Based on these results, we speculate that RUNX1 may be essential for the survival of prostate cancer cells as AR is the key signal factor in clinical prostate cancer progression." (PMID 25537508, 2015). "Similarly, we propose that targeting RUNX1, for example, using microRNAs as described for prostate cancer, or other molecular or pharmacological approaches, might also result in amelioration of the cystic phenotype." (PMID 31773180, 2019). "Thus, we consider RUNX1 as a target of EZH2 in prostate cancer." (PMID 25537508, 2015). "We analyzed whether RUNX1 is involved in androgen-independent prostate cancer development." (PMID 25537508, 2015). "Therefore, AR-independent and RUNX1-regulated signals, which remain to be clarified, may be important for prostate cancer progression." (PMID 25537508, 2015). "The transcriptional activities of NKX2-5, RUNX1, TRPS1, FOXO1, and TP63 are negatively correlated with LEGs, suggesting these suppress prostate cancer lineage plasticity through the RTK/RAS pathway." (PMID 38778150, 2024). "NKX2-5, RUNX1, TRPS1, FOXO1, and TP63 play a inhibitory roles in the development of prostate cancer." (PMID 38778150, 2024). "Not only did this approach suppress the prostate cancer EMT and metastasis through the regulation of the Akt/JNK and P38 MAPK pathways, but it also halted RUNX1-targeted EMT/metastasis strategies." (PMID 37367670, 2023). "Runt-related transcription factor 1 (RUNX1) correlates with poor prognosis in TNBC and is regulated by the AR in prostate cancer." (PMID 36766786, 2023). "Taken together, HA has an efficacy to suppress the migratory and invasion potential of prostate cancer PC3 and LNCaP cells as well as overexpressing RUNX1 in PC3 cells via the downregulation of MMP2 and MMP9." (PMID 37367670, 2023). "The persistent elevation of Runx1 and Runx2 transcription factors in TRAMP prostate tissue throughout progression to adenocarcinoma suggests a pro-tumorigenic role in prostate cancer." (PMID 27634876, 2016). "PIM2 and runt-related transcription factor 1 (RUNX1) oncogenes have critical role in the development of several kinds of tumors, including prostatic carcinoma." (PMID 23023193, 2012).
prostate carcinoma (continued). "RUNX1 was reported as a target of AR, and its promoter was bound by EZH2 in prostate cancer." (PMID 29921304, 2018). "The TRAMP mouse is ideal to study the dynamic expression of Runx1 and Runx2 in the transition from a normal gland to tumorigenic tissue as TRAMP prostates develop morphologically and histologically similar tumors to human prostate cancer." (PMID 27634876, 2016). "In contrast, a reduction in RUNX1 expression, not overexpression, is required to prevent AR-independent growth inhibitory effect on prostate cancer cells." (PMID 25537508, 2015). "The poor outcome of prostate cancer with low expression of RUNX1 could be in line with this negative role of RUNX1 in prostate cancer growth." (PMID 25537508, 2015). "Considering the PCa, all we know is that RUNX1 and RUNX2, but not RUNX3, are highly expressed in PCa tissues, the primary prostatic carcinoma cell line, and the LNCaP and PC3 PCa cell lines." (PMID 37367670, 2023).
chronic myeloid leukemia (28 papers, 2010 to 2025). "RUNX1 was involved in implicated in chronic myeloid leukemia and transcriptional misregulation of cancer signaling pathways." (PMID 39272372, 2024). "Lastly, one variant is mapped to the RUNX1 gene associated with chronic myeloid leukemia." (PMID 38291454, 2024). "Chronic myeloid leukaemia also has a high rate of Runx1 mutation in BP." (PMID 24571310, 2014). "Blast-phase chronic myeloid leukemia (BP-CML) is associated with additional chromosomal aberrations, RUNX1 mutations being one of the most common." (PMID 32782381, 2021). "Previously, we observed that transcription factor RUNX1 mutations (RUNX1-MT) coexisted with ASXL1-MT in CMML and at myeloid blast phase of chronic myeloid leukemia." (PMID 31640815, 2019). "In addition, the BCR–ABL, Tax-1, RUNX1, and NUP98–HOXA9 (NA9) fusion proteins associated with chronic granulocytic leukemia (CML) and acute myeloid or lymphoid leukemia (AML/ALL) have also been found to cause leukemia-like traits in Drosophila lymph glands." (PMID 36831328, 2023). "Other data suggested that the RUNX1/PRDM16 fusion gene could contribute to immortalization of the leukemic stem cell and play an important role during clonal evolution from chronic myeloid leukemia (CML) to AML and imatinib resistance." (PMID 32290321, 2020).
ovarian carcinoma (27 papers, 2013 to 2026). A malignant neoplasm originating from the surface ovarian epithelium. "In ovarian cancer, the dysregulation of the RUNX1 signaling pathway has been implicated in tumor progression, metastasis, and response to therapy." (PMID 37760803, 2023). "Among different types of cancer, changes in RUNX1 expression are associated with female-related cancers such as breast cancer, uterine cancer, and ovarian cancer." (PMID 37760803, 2023). "Several studies have demonstrated that RUNX1 expression is closely associated with the progression of solid tumors, such as ovarian cancer, glioblastoma, and renal cancer." (PMID 35534796, 2022). "Both the amplification and deletion of the RUNX1 gene have been associated with ovarian cancer in humans." (PMID 36430923, 2022). "Among the differentially expressed gene that were associated with ovarian cancers, Cdh1, encoding E-Cadherin, was strongly downregulated in Runx1 KO ovaries." (PMID 36430923, 2022). "RNA-sequencing analysis of 4.5-month-old Runx1 KO ovaries revealed differential expression of genes associated with ovarian cancer." (PMID 36430923, 2022). "Therefore, to determine whether loss of Runx1 in these cell populations could lead to these types of ovarian cancer, we generated a conditional knockout mouse model, in which Runx1 was specifically ablated from the somatic cells of the ovary." (PMID 36430923, 2022). "In epithelial ovarian cancer, circMUC16 can promote the expression of Beclin-1 and Runx1 by sponging miR-199a-5p, thus promoting autophagy." (PMID 38338839, 2024). "Several studies on ovarian cancer have found that RUNX1 can promote cell proliferation, migration, and invasion of ovarian cancer." (PMID 37760803, 2023). "Subsequently, flow cytometry analysis results indicated that the cell portion of apoptosis was significantly increased in RUNX1 knockdown ovarian cancer cell lines (SKOV3, OVCAR3)." (PMID 38057816, 2023). "RUNX1 expression in ovarian cancer cells has been found to promote the proliferation and migration of ovarian cancer tumor cells." (PMID 38057816, 2023). "This study found that reducing the expression of RUNX1 gene significantly increased the inhibitory effect of taxane, paclitaxel, carboplatin, or cisplatin on the proliferation of ovarian cancer cells." (PMID 38057816, 2023). "This further demonstrates the importance of RUNX1 in ovarian cancer and justifies the need for in-depth research on RUNX1." (PMID 37760803, 2023). "The physiological functions were evaluated in RUNX1 knockdown ovarian cancer cells, such as proliferation, migration, and invasion." (PMID 38057816, 2023). "In summary, RUNX1 plays an essential role in the development of ovarian cancer and can regulate the function of ovarian cancer through multiple pathways." (PMID 37760803, 2023). "It has been suggested that the combination of chemotherapy drugs (taxane, paclitaxel, and platinum agents) with the deletion of RUNX1 gene can be more effective against chemoresistant ovarian cancer." (PMID 38057816, 2023). "Previous studies have reported that RUNX1 is significantly highly expressed in ovarian cancer and can also regulate many functions of tumor cells, indicating that RUNX1 is crucial in the regulation of ovarian cancer." (PMID 37760803, 2023). "In our study, knockdown of RUNX1 significantly increased the proliferation inhibition of ovarian cancer cells treated with taxane, paclitaxel, and platinum drugs (carboplatin or cisplatin)." (PMID 37760803, 2023). "It is worth noting that the RUNX1 pathway in ovarian cancer is still an active area of research, and further studies are required to fully elucidate its molecular mechanisms and therapeutic potential." (PMID 37760803, 2023). "Genetic alterations in RUNX1 have previously been identified in 1.5% of ovarian cancers, according to publicly available data from The Cancer Genome Atlas (TCGA)." (PMID 37760803, 2023).